MYD88 (MYD88 innate immune signal transduction adaptor)
Diseases named in the same sentence as MYD88 in open-access papers (continued):
Sharing a sentence is not in itself a finding about the gene and the disease.
lymphoma (continued). "In our hands the largest subgroup of patients consisted of those with shared MYD88 mutations in both lymphoma types, but harbored different IGH clonal peaks." (PMID 33180881, 2020). "In aggressive lymphomas, BTK inhibitors appear to be of particular benefit in lymphomas with activating mutations in MYD88 and CD79B." (PMID 33363034, 2020). "We therefore investigated a role for SYK as a mediator of BCR activation in MYD88-mutated lymphomas." (PMID 32005797, 2020). "We therefore investigated a role for SYK as a mediator of TLR/BCR cross talk in MYD88-mutated lymphomas." (PMID 32005797, 2020). "For the indolent lymphomas, the patients with Waldenström’s macroglobulinemia all had the hallmark MYD88 mutation, and three of those also had a CXCR4 mutation, both very frequent mutations in this disease." (PMID 32013121, 2020). "Our findings extend the spectrum of mutated MYD88 pro-survival signaling to include SYK directed BCR cross talk in MYD88-mutated lymphomas." (PMID 32005797, 2020). "We next performed PhosFlow studies for SYK in MYD88-mutated lymphoma cells following treatment with a MYD88 inhibitor or control peptide." (PMID 32005797, 2020). "Most cases have an ABC-like phenotype with upregulation of the NF-κΒ pathway, characteristically induced by EBV latent membrane protein-1 (LMP1), which explains the rarity of CD79B and MYD88 mutations in these lymphomas." (PMID 33178841, 2020). "The two patients with clonally unrelated lymphoma both presented with high risk features (one with a MYD88 mutation and one with a Burkitt‐like phenotype of DLBCL)." (PMID 31124124, 2019). "Lymphoma cells shed EV with mutated MyD88, which induces a proinflammatory BM microenvironment and causes BM niche deregulation and inefficient haematopoiesis." (PMID 31281380, 2019). "Large B-cell lymphoma cells harbour a mutation in MyD88 (myeloid differentiation primary response 88) gene, a key signalling molecule that interacts with Toll-like and IL-1 receptors and sustains lymphoma cell survival." (PMID 31281380, 2019). "We isolated CSF-ctDNA and used droplet digital PCR (ddPCR) to detect the most common lymphoma-associated mutations in MYD88, L265P, and V217F." (PMID 30294590, 2018). "The importance of gaining insight of the impact of MYD88 mutations in combination with other genomic events in lymphoma is further supported by recent findings showing a correlation between MYD88 mutation status and poor outcome in DLBCL33." (PMID 30301877, 2018). "Studies in others extra-nodal lymphomas, such as central nervous system and testis lymphomas, also showed MYD88, CD79B and PIM1 as the most frequently mutated genes, and points out a common molecular profile for extra-nodal DLBCL." (PMID 29262531, 2017). "Patients harboring a MYD88 mutation in their lymphoma exhibited a significantly shorter DFS as compared to patients with wild type MYD88 (p=0.006)." (PMID 27566587, 2016). "Given that intact TLR activity is critical for lymphoma cells carrying MYD88 mutations, targeting this pathway appears to be attractive for treating these malignancies." (PMID 25132836, 2014). "shRNA knockdown of MYD88 in lymphoma cell lines demonstrated that MYD88 mutations are critical for their survival and high NFκB transcription factor activity." (PMID 25132836, 2014). "Activation of TLRs by MYD88 mutations has often been associated with poor clinical outcome in lymphoma patients." (PMID 25132836, 2014). "Other peptide-based synthetic small molecule inhibitors such as hydrocinnamoyl-l-valyl pyrrolidine (compound 4a) and Pephinh-MYD88 have also been developed to target MYD88 dimerization in the treatment of lymphoma patients with MYD88 mutations." (PMID 25132836, 2014). "Of interest, the two SMZL cases with mutations of CD79B and MYD88, respectively, showed increased numbers of immunoblasts spread among the smaller and typical marginal zone lymphoma cells." (PMID 23378931, 2013).
lymphoma (continued). "Of importance, biological evidence has indicated that these recurrent genetic mutations of the MYD88 gene in lymphoma, particularly the hot-spot alteration of L265P in the TIR domain, is a gain-of-function mutation." (PMID 23976989, 2013). "MYD88 mutations are often observed in paired diagnostic and relapsed samples, suggesting they occur early in the disease process and persist through relapses in certain types of lymphoma." (PMID 40507216, 2025). "In particular, the use of MYD88-cfDNA seems promising, as this marker represents a lymphoma-specific mutation, which may carry a low prior risk of non-specific or false-positive findings." (PMID 40723236, 2025). "A potential limitation of our study is that we focused solely on MYD88 L265P, the most prevalent mutation found in lymphomas; other MYD88 variants, such as S222R and T294P, could be responsible for the altered protein expression." (PMID 38335426, 2024). "Previous studies have reported transcriptomic profiles of primary lymphoma cells bearing MyD88 mutations; however, to the best of our knowledge, this is the first study solely addressing the transcriptomic response of MyD88L265P in a well-characterized and tightly controlled cellular model system." (PMID 36982699, 2023). "Recently, it was shown that frequent lymphoma-associated mutations of MYD88 (myeloid differentiation primary response 88) adaptor protein lead to its spontaneous association with Toll-like receptor 9 (TLR9) and BCR, forming a My-T-BCR complex capable to trigger NF-κB activation." (PMID 38203179, 2023). "Analyzing the publicly available dataset GSE94669, we could also notice that even though CD44 is a known marker for ABC DLBCL classification, CD44 levels are consistently higher in lymphoma cell lines expressing mutated MyD88." (PMID 36982699, 2023). "Thirty‐four of 113 (30%) of the lymphomas harbored both MYD88 and CD79B mutations." (PMID 36051079, 2022). "However, there is a tendency to a lower OS in patients with MYD88 mutations than in patients with lymphomas from other sites, which is in line with the poor outcome of patients from “cluster 5” or MCD type." (PMID 36051079, 2022). "There were totally 9 patients that harbored MYD88 L265P mutation; it was functional gain-driven mutation and located in the MYD88 Toll-like/interleukin- (IL-) 1 receptor domain, which is related with unfavourable prognosis among aggressive lymphoma." (PMID 35937947, 2022). "MYD88 is an important oncogene that can be recurrently mutated in several types of lymphoma." (PMID 35628381, 2022). "Thirty percent of the lymphomas in our cohort harbored both MYD88 and CD79B mutations." (PMID 36051079, 2022). "In addition to its physiological role in the immune response, MYD88 can also act as an oncogene associated with lymphoma development, and somatic mutations have been identified in numerous patients." (PMID 35628381, 2022). "Moreover, lymphoma is more likely to invade and metastasize due to the mutation of MYD88 or BCL6 genes and the action of multiple immune cells in the tumor microenvironment." (PMID 35712495, 2022). "Panel sequencing of the lymphoma showed mutations in MYD88 (p.Ser219Cys) and NOTCH2 (p.Gln2409Ter)." (PMID 33876323, 2021). "Furthermore, by knockdown studies as well as use of SYK inhibitors, we validated the importance of SYK as an essential pro-survival molecule in MYD88-mutated lymphoma cells." (PMID 32005797, 2020). "We therefore have sought to clarify whether mutated MYD88 could account for chronic BCR signaling in MYD88-mutated lymphoma cells." (PMID 32005797, 2020). "Importantly, the combination of SYK inhibitors with ibrutinib yielded synergistic lethality in MYD88-mutated lymphoma cells." (PMID 32005797, 2020).
lymphoma (continued). "Since MYD88 L265P mutation is a hallmark of lymphoma with lymphoplasmacytic features and activated NF-κB signaling pathway, the higher frequency of MYD88 mutations in the ABC phenotype suggests that this subtype may derive from cells with those features." (PMID 25984532, 2015). "Activating mutations in MyD88 have been described in human lymphomas, suggesting that constitutive human TLR7 or TLR8 signaling in our mice could be driving proliferation." (PMID 25229618, 2014). "We examined whether compounds reported to inhibit the activity or activation of the canonical IKK complex also inhibited the proliferation of HBL-1 lymphoma cells expressing the MyD88[L265P] mutation." (PMID 23441730, 2013). "Interestingly, the two cases with mutations of CD79B and MYD88 showed increased numbers of immunoblasts spread among the smaller and typical marginal zone lymphoma cells." (PMID 23378931, 2013). "Of note, only one of the 40 patients examined for MYD88 mutation had prior history of lymphoma." (PMID 23976989, 2013). "In the second experiment, cultivated MYD88-positive lymphoma cells derived from a commercially available cell line were used." (PMID 41590411, 2026). "Gain-of-function CD79 and MyD88 mutations hyperactivate BCR/TLR9 signaling in several types of lymphoma, including the diffuse large B cell lymphoma (DLBCL) MyD88/CD79B-mutated (MCD) subtype." (PMID 40924473, 2025). "We reanalyzed RNA-seq data generated from B-cell-purified lymphomas that formed on an Eμ-myc;MyD88-L265P background, and found a strong enrichment for myeloid signatures in the MyD88-L265P vs. Myc-only driven lymphomas." (PMID 40159497, 2025). "Mutational profile in lymphomas of immune-privileged sites includes concomitant MYD88 and CD79B mutations with genomic signature C5/MCD/MYD88 and genetic inactivation of MHC class I and II and β2-microglobulin with subsequent loss of protein expression." (PMID 39352469, 2025). "PCNSL and SCNSL were expected to be very similar as both need to adapt to the CNS environment; only MYD88 and PIM1 mutations and lymphoma translocations showed differing abundances." (PMID 40346678, 2025). "The patient with the MYD88 L265P mutation (ECD5) developed CNS involvement and died of lymphoma 42 months after diagnosis, despite second-line treatment with radiotherapy and immune-polychemotherapy (R-CHOP)." (PMID 40511879, 2025). "Empirical evidence suggests that butyrate-producing Eubacterium inhibit lymphoma development by attenuating the TNF-activated TLR4/MyD88/NF-κB signaling cascade." (PMID 38774867, 2024). "These patients have previously been published as part of a prior study (n = 34) investigating MYC, BCL2, and BCL6 rearrangements, pathogenic variants of MYD88 and CD79B, and double-expressor lymphoma." (PMID 38542066, 2024). "Sequence studies of the entire exome and transcriptome of lymphoma tissues have identified MYD88 and PIM1 as involved in the development and oncogenic signaling." (PMID 38335426, 2024). "Specifically, it prevents lymphoma by modulating the TNF-induced TLR4/MyD88/NF-κB axis, thereby reducing lymphoma incidence in Eμ-Myc mice." (PMID 39619672, 2024). "Lastly, we show that expression of MYD88-S257D can rescue cell growth upon silencing of endogenous MYD88-L265P expression in lymphoma cells addicted to oncogenic MYD88 signaling." (PMID 37591861, 2023). "We established an inducible system to introduce MyD88 to lymphoma cell lines and performed transcriptomic analysis (RNA-seq) to identify genes differentially expressed by MyD88 bearing the L265P oncogenic mutation." (PMID 36982699, 2023). "Another target for ctDNA analysis is the PCNSL tumour-specific MYD88 L265P mutation due to its presence in more than 80% of PCNSL tumours and very rare detection on other non-lymphoma CNS malignancies." (PMID 37240953, 2023).
lymphoma (continued). "MYD88 S257D did not only promote cell growth of MYD88 wildtype cells, but, remarkably, was also able to sustain cell growth of MYD88 L265P-addicted lymphoma cells after silencing of endogenous (mutant) MYD88." (PMID 37591861, 2023). "Our findings suggest that these compounds will not only be effective in MYD88 L265P-expressing lymphomas, but also in lymphomas in which MYD88 activation is regulated by other means, such as phosphorylation." (PMID 37591861, 2023). "MYD88, CD79B, and other NF-κB-pathway-related mutations promote IL-10 expression by lymphoma cells, and IL-10 has also been found to express in CD68+ and CD163+ tumor-associated macrophages by double immunostaining analysis." (PMID 36644235, 2023). "Despite intensive research, however, the immediate consequences of MyD88L265P expression in lymphoma cells, the exact molecular mechanism of MyD88 oncogenic signaling, and its role in other pathways beyond NF-kB activation remain unresolved." (PMID 36982699, 2023). "RT-qPCR results showed that the mRNA expression of Myd88 in lymphoid cancer cell lines OCl-LY7, FARAGE and U2932 was upregulated compared with human lymphoblastoid B cells GM12878." (PMID 37953776, 2023). "Next, having established and validated the MyD88 inducible system in lymphoma cells, we wanted to reveal the global effects of acute MyD88L265P expression at the transcriptome level." (PMID 36982699, 2023). "Only FOXO1, BTG1, and MYD88 were in line with expectations, indicating that the abnormal transcriptional pattern for specialized lymphoma was very complicated due to the heterogeneity of lymphoma." (PMID 37700827, 2023). "MYD88, CD79B, and/or BTK mutated lymphomas had a lower OS and PFS, which can mostly be attributed to the group of primary CNS lymphomas." (PMID 36051079, 2022). "Some of these genes (such as the BTG2 gene, MYD88 gene and IL-25 genes) have been found to be closely related to the progression, chemotherapy resistance and inferior OS of lymphoma, and some have become potential therapeutic targets." (PMID 36221115, 2022). "Therefore, it could be hypothesized that lymphomagenesis is driven by the interaction of microbial or viral ligands with the TLR and the subsequent changes in the upstream pathway of MyD88-mutated lymphomas, which may be different in tumor cells and ‘normal’ cells." (PMID 35628381, 2022). "In the established lymphomas, NF-κB activity is further enforced by mutations in various genes regulating NF-κB activity (e.g., TNFAIP3, MYD88), as well as recurrent chromosomal translocations affecting NF-κB pathway components in a subset of cases." (PMID 35267569, 2022). "Collectively, this suggests that, contrary to expectations, lymphoma samples show a higher ratio of canonical MyD88 (isoform 2) to MyD88s (isoform 3) than naive B cells." (PMID 34163463, 2021). "Several MyD88 TIR domain missense mutations (V204F, S206C, I207T, S209R, S230N, M219T, L252P and T281P) sustain lymphoma cell survival due to constitutive NF-κB signaling." (PMID 33972532, 2021). "Further to these findings, we performed cellular co-localization experiments using immunofluorescent (IF) with antibodies for MYD88 and SYK in both MYD88-mutated and wild-type lymphoma cells." (PMID 32005797, 2020). "Since SYK was activated by mutated MYD88, we next sought to clarify if SYK and p-SYK were present in the “Myddosome” signaling complex in MYD88-mutated lymphoma cells." (PMID 32005797, 2020). "We identified activated SYK (p-SYK), a component of BCR in complex with MYD88 in MYD88-mutated WM and ABC DLBCL lymphoma cells." (PMID 32005797, 2020).
lymphoma (continued). "The distinction between certain lymphomas can be problematic and in this case MYD88 was helpful in clarifying a diagnosis of atypical LPL/WM from MZL and in selecting effective second-line therapy." (PMID 28286680, 2017). "One strategy to compensate for the lack of WM models is to compare the activity of drugs in lymphoma models sharing similar mutations to WM, like those of MYD88." (PMID 41447345, 2025). "Moreover, MyD88-L265P-driven lymphomas enriched for PU.1 and C/EBPβ gene sets, and exhibited high-level expression of the respective TF and their target genes, such as Csf1r and Il1b." (PMID 40159497, 2025). "MYD88 was expressed in lymphoma cells in 8 (16%) of 50 cases." (PMID 38335426, 2024). "In lymphomas, CD79B mutations also commonly co-occur with MYD88 mutations, especially MYD88L265P." (PMID 38203179, 2023). "Following silencing of endogenous MYD88 in L265P-expressing lymphoma cells lines, cell growth could only be sustained by mutant, but not wildtype MYD88, demonstrating that L265P is a gain-of-function mutation." (PMID 37591861, 2023). "Importantly, we found that the phosphomimetic MYD88 S257D and oncogenic L265P mutant were equally capable of promoting lymphoma cell growth." (PMID 37591861, 2023). "It is therefore hypothesized that f_Enterococcaceae may be involved in lymphoma development by acting on MYD88 and activating NF-κB signaling." (PMID 36891300, 2023). "The regulation of TLR/MYD88 signaling in lymphomas without MYD88 mutations, as well as in healthy B cells, is incompletely understood." (PMID 37591861, 2023). "Next, miR-525-5p targets the 3′-UTR of Myd88, and Myd88 protein was increased in lymphoma tissues." (PMID 37953776, 2023). "In particular, MyD88 was reported to play a role in the occurrence and development of breast cancer, epithelial ovarian carcinoma, human hepatocellular carcinoma, osteosarcoma, adenocarcinoma of the colon, and hematopoietic cancer-like lymphoma and leukemia." (PMID 37749630, 2023). "Laboratory investigations revealed IgMκ monoclonal protein and MYD88 L265P mutation, but no lymphoplasmacytic lymphoma on bone marrow examination." (PMID 35514998, 2022). "In our study, we found ECOG score 3–4 was closely associated with mutations in MYD88, MALT1, and ROS1, which suggested that ECOG might be associated with lymphoma heterogeneity." (PMID 35865478, 2022). "The absence of MYD88 mutations in WM patients has been associated with a higher risk of transformation into aggressive lymphoma, resistance to certain therapies (BTK inhibitors), and shorter overall survival." (PMID 35628381, 2022). "This is consistent with animal models, where MYD88 mutations are not sufficient for the development of WM or other MyD88-driven lymphomas, and additional alterations in tumor cells and/or the host response are needed." (PMID 35628381, 2022). "A high incidence of MYD88 and CD79B mutations was also detected in the ENT lymphomas in our cohort." (PMID 36051079, 2022). "MYD88 mutations occur mainly monoallelic in over 90% of patients with WM and with this are by far most common though not specific for this lymphoma subtype." (PMID 33273682, 2021). "Therefore, we conclude that proliferating B cells, like lymphoma samples, show and maintain a preference for canonical MyD88 signaling." (PMID 34163463, 2021). "Patients with lymphoma involvement in breast had higher MYD88 (36.4 vs. 10.5%, P = 0.049) mutations than those without breast involvement." (PMID 34557402, 2021). "Indeed, they tested multiplexing of these probes with two others designed for two additional lymphoma-related hotspots (L265P of MYD88 and I290R of CCND3), allowing the simultaneous detection of distinct mutations." (PMID 32365599, 2020).